KIT (KIT proto-oncogene, receptor tyrosine kinase)
Diseases named in the same sentence as KIT in open-access papers (continued):
Sharing a sentence is not in itself a finding about the gene and the disease.
infection (50 papers, 2011 to 2025). The state of being infected such as from the introduction of a foreign agent such as serum, vaccine, antigenic substance or organism. "The third cluster included genes that were moderately expressed in CDH5+ cells, highly expressed in c-KIT+ populations, and associated with ontology terms such as development of the hematopoietic program, leukocyte migration, chemotaxis, and response to infection/wounding ontology terms." (PMID 25466247, 2014). "Infection of these differentiated cells with lenti-virus (IRES-GFP) coding for the KITD816V allele reiterates the TET2 and KIT mutations found in patient mast cell clones." (PMID 35393954, 2022). "Another possibility is that Yersinia interacts with lipid rafts containing c-KIT in the plasma membranes of host cells during the infection process." (PMID 24206648, 2013). "Similarly, expression levels of the NF-κB transcription factors, NF-κB1/p50 and RelA/p65, were recovered in c-KIT-silenced cells in response to Y. enterocolitica WA infection." (PMID 24206648, 2013). "In addition, SCF activation of KIT is critical for recruiting mast cells to sites of infection or injury, where they release a mix of pro-inflammatory substances." (PMID 23185384, 2012). "Prior to infection, these cells were depleted of any CD41-, CD31-, c-KIT-, and CD45-positive cells to eliminate potential contamination by hematopoietic and endothelial cells." (PMID 25466247, 2014). "However, not all signaling pathways are inactivated by Yersinia during infection, and inhibition of c-KIT may lead to redirection to alternative signaling pathways, such as the LPS-activated CD14 and TLR4 signaling to p38 and JNK, to recover NF-KB-driven gene expression." (PMID 24206648, 2013). "In this study, we showed that KITLG expression was significantly suppressed after infection with miR-34c, and the miR-34c-induced down-regulation of KITLG inhibited proliferation but promoted apoptosis in CRC cells that concomitantly express c-KIT and KITLG." (PMID 25213795, 2014). "Inhibition of c-KIT with OSI930 fully restored EGR1 levels in cells infected with virulent Y. enterocolitica and significantly recovered transcription of IL-8 and CCL20 at 5 h and 20 h post-infection (dark grey bars)." (PMID 24206648, 2013). "In the absence of infection, silencing of c-KIT expression by siRNA did not induce any significant change in the expression levels of EGR1 or the tested cytokines and transcription factors." (PMID 24206648, 2013). "We also show that ~95% depletion of c-KIT transcript levels by siRNA treatment rescued EGR1, VCAM1, CCL20, and IL-8 gene expression in response to Y. enterocolitica WA infection in THP-1 cells, compared to infected control cells treated with non-targeting siRNA (si-CTL)." (PMID 24206648, 2013). "In addition, we demonstrated that lentiviral infection of ROSAKIT D816V cells with the Gluc-containing construct did not alter their morphology, the KIT D816V expression, the constitutive phosphorylation of the KIT receptor, and their SCF-independence." (PMID 27783996, 2016).
gastrointestinal tumors (26 papers, 2007 to 2025). "GIST is a rare gastrointestinal tumor originating from Cajal mesenchymal stromal cells, its pathogenesis mainly involves mutations in the c-KIT or PDGFRA genes." (PMID 40837560, 2025). "This patient had a KIT exon 11 mutated gastro-intestinal tumour for which he received imatinib and consecutively sunitinib." (PMID 35606463, 2022). "Dysregulation or mutation of KIT is known to be associated with gastrointestinal tumors." (PMID 33362856, 2020). "Furthermore, also in gastro-intestinal tumors KIT mutation rate is lower than the expression rate of KIT." (PMID 22937135, 2012). "Since the microphthalmia factor (MITF) has been described as regulating KIT expression (mainly in murine MCs and human gastrointestinal tumors), we finally compared CREB to MITF." (PMID 38201246, 2023). "It has been shown that in gastrointestinal tumors miR-222 induces apoptosis through the activation of KIT and AKT pathway." (PMID 33901254, 2021). "Imatinib has also shown some effectiveness in the treatment gastrointestinal tumors with mutant KIT." (PMID 23185384, 2012). "The presence of KIT mutations does not appear to be related either to the GISTs localization, nor to the histotype and to the histological grade of the GI tumors." (PMID 35878393, 2022). "Finally, a thirteen-year-old female with a stomach GIST with positive c-KIT diagnosis (CD-117) by immunohistochemistry is currently receiving imatinib after radical surgery and has achieved complete response." (PMID 33916788, 2021). "Activated KIT is reported to prolong ETV1 protein stability and cooperate with ETV1 to promote tumorigenesis in gastrointestinal tumours." (PMID 32580154, 2020). "Unlike other gastrointestinal neoplasms, more than 90% of GISTs express the KIT proto-oncogene, as measured by immunohistochemical analysis of CD117, the stem cell factor receptor protein encoded by KIT." (PMID 23637977, 2013).
hematological malignancies (20 papers, 2006 to 2025). "Patients with hematopoietic diseases like AML mostly show mutations in the A-loop region of the KIT gene, the most prominent ones being mutations at D816 and N82224." (PMID 36396684, 2022). "IL-6, in the cellular context of KIT mutations, not only induces DJ-1 expression in mast cells, it promotes secretion of ROS into the extracellular space, a feature that has been linked to some hematological malignancies and to cell transformation in general." (PMID 27611333, 2016). "This activity supports exploration of avapritinib in other KIT D816V-positive hematologic malignancies." (PMID 34873345, 2021). "Gain-of-function mutations of the FLT3, KIT and PDGFR class III receptor tyrosine kinases (RTK) play important roles as oncogenesis-driving events in several hematologic malignancies." (PMID 23497317, 2013). "Imatinib is a KIT-targeted TKI that is approved for patients with multiple hematologic malignancies, including adult patients with ASM without the KIT D816V mutation or with unknown KIT mutational status (Gleevec package insert." (PMID 26002753, 2015).
adenocarcinoma (15 papers, 2015 to 2025). A common cancer characterized by the presence of malignant glandular cells. "The KIT expression was found to be weak in two samples and moderate in one sample, AR was moderately expressed in both patients with adenocarcinoma." (PMID 33296026, 2021). "We have also investigated the immunohistochemical expression of the ETV1 in the synchronous GISTs and adenocarcinomas since it was described as a transcription factor responsible for the differentiation of the interstitial cells of Cajal and to cooperate with KIT to promote GIST tumorigenesis." (PMID 33335133, 2020). "A study was performed with a customized NGS panel (called SiRe) including six genes [EGFR, KRAS, NRAS (NRAS Proto-Oncogene, GTPase), BRAF, KIT Proto-Oncogene Receptor Tyrosine Kinase (KIT)), Platelet-Derived Growth Factor Receptor Alpha (PDGFRA)] for 194 patients with advanced adenocarcinomas." (PMID 33922637, 2021).
hematopoietic neoplasms (6 papers, 2014 to 2025). "In these subpopulation, a KIT D816V mutation was present in all the 13 patients with ISM (100%) and in the patient with ISM with an associated haematological neoplasm (100%), of the patients with MMAS 2 of the 6 patients presented the mutation (33%)." (PMID 35281031, 2022). "By examining statistical independence between pairwise dependency profiles, we identify additional pairs of proteins that share short loop commonality and exhibit either mutual exclusivity (as does FLT3 and KIT) or co-occurrence of dependency in haematopoietic cancer cell lines." (PMID 33709075, 2021). "It is worth noticing that although PDGFRα and KIT are expressed in a variety of human hematopoietic neoplasms, the chromosomal region where both genes are located (HSA 4q12) is frequently deleted in hDLBCL, evidence totally in contrast with what observed herein." (PMID 25372838, 2014). "To determine whether CDK6 is a common essential effector of oncogenic tyrosine kinases, we evaluated its contribution downstream of oncogenic KIT, a receptor closely related to FLT3 also involved in hematopoietic neoplasms." (PMID 27323399, 2016).
bacterial infection (5 papers, 2013 to 2025). "Inhibition of JNK1, acting downstream of c-KIT signaling, with the small molecule BI-78D3 did not exhibit any protective effect on gene transcription (medium grey bars) at either time point of bacterial infection, compared to drug-free cells (light grey bars)." (PMID 24206648, 2013).
neurodegenerative disease (4 papers, 2011 to 2024). A disorder of the central nervous system characterized by gradual and progressive loss of neural tissue and neurologic function. "The effects of c-KIT on mast cells have evolved as therapeutic targets for several neurodegenerative diseases." (PMID 39009412, 2024).
cardiovascular disease (2 papers, 2014 to 2025). "While platinum-based chemotherapy remains highly effective, it does pose its own array of barriers, including treatment-induced toxicities, such as secondary malignancies and cardiovascular disease, and platinum-resistant cases associated with KIT and RAS mutations." (PMID 41154418, 2025).
autosomal dominant disease (1 paper, 2022). Autosomal dominant form of disease. "Piebaldism is a rare autosomal dominant disease, and roughly 75% patients had KIT gene mutations." (PMID 36438053, 2022).
psychiatric disorder (1 paper, 2020). A disorder characterized by behavioral and/or psychological abnormalities, often accompanied by physical symptoms. "The seven other psychiatric disorders also all had at least one significant genic association, ranging from 121 Bonferroni significant associations for BIP, to just one for OCD (Kit Proto-Oncogene, Receptor Tyrosine Kinase [KIT], P = 2.3 × 10−7)." (PMID 32398653, 2020).
respiratory disease (1 paper, 2019). "In Chinese Erhualian pigs, QTLs affecting respiratory disease were identified by a genome-wide association study; CXCL6, CXCL8, KIT, and CTBP2 were highlighted as candidates that might associated with resistance or susceptibility to swine enzootic pneumonia-like respiratory disease." (PMID 31656701, 2019).
KIT also shares sentences with these, for which no sentence is quoted: synovial sarcoma (17 papers); Constipation (16); hematologic neoplasm (14); chromophobe renal cell carcinoma (12); acute promyelocytic leukemia (10); neuroendocrine tumors (10); rhabdomyosarcoma (10); breast tumors (9); ischemia (9); desmoid tumor (8); multiple myeloma (8); Kaposi's sarcoma (7); lung (7); salivary gland tumors (7); Sepsis (7); atherosclerosis (6); endometrial cancer (6); Infertility (6); malignant peripheral nerve sheath tumor (6); pheochromocytoma (6); solitary fibrous tumor (6); cardiac diseases (5); clear cell sarcoma (5); dermatofibrosarcoma protuberans (5); heart failure (5); leukocytosis (5); PEComas (5); sarcomatoid carcinoma (5); soft tissue tumors (5); alveolar rhabdomyosarcoma (4).
A further 418 diseases each share a sentence with KIT in 4 papers or fewer.